INS (insulin)
Diseases named in the same sentence as INS in open-access papers (continued):
Sharing a sentence is not in itself a finding about the gene and the disease.
diabetes (continued). "Resistin was first described as a factor contributing to the development of insulin resistance and diabetes mellitus in humans; a debate is still ongoing regarding its exact role in obesity, in insulin sensitivity, and in the development of type 2 diabetes mellitus (DM2)." (PMID 27746590, 2016). "Thiazolidinediones, which are PPAR-γ agonists, have been used for years as insulin sensitizers in diabetes mellitus type 2, but they have been gradually removed from the market because of hepatotoxicity, increased cardiovascular risk, or increased occurrence of bladder cancer." (PMID 27445808, 2016). "Evidence has accumulated that oxidative stress plays a key role in the pathogenesis of diabetes-induced cardiovascular disease, which is also closely related to the insulin resistance and impaired insulin secretion that lead to the development of diabetic complications." (PMID 27399653, 2016). "Effects of insulin and other factors, including inflammation in the brain, need further consideration as plausible underlying mechanisms linking insulin resistance, with and without diabetes/pre-diabetes, to dementia." (PMID 27303627, 2016). "Diabetes mellitus has been described as a metabolic disorder of multiple aetiology, and characterized by chronic hyperglycemia with disturbances of carbohydrate, fat, and protein metabolism, resulting from defects in insulin secretion, insulin action or both." (PMID 27846886, 2016). "It is synthesised from isoleucine and has been postulated as one of the molecules responsible for the antidiabetic effects in animals because of its ability to regulate pancreatic insulin secretion, hence it has significant potential for the treatment of IR and diabetes." (PMID 27879673, 2016). "Mice carrying the Ins2C96Y mutation develop progressive diabetes mellitus, a phenotype that probably reflects a holistic effect rather than just the loss of correctly folded insulin production by the mutant Ins2 allele." (PMID 27595114, 2016). "Mutations in Ataxia Telangiectasia Mutated (ATM) that cause ataxia telangiectasia are associated with elevated glycaemia and low insulin sensitivity in participants without diabetes." (PMID 26606753, 2016). "Moreover the insulin levels in Fukuoka men with diabetes were significantly lower than those values in Framingham NGT men (P < 0.001), similar to the population differences in women." (PMID 27830830, 2016). "More recently, before the insulin era began, doctors had been prescribing exercise for diabetes." (PMID 27073714, 2016). "Therefore, both have been tested as replacement insulin producing cells for diabetes cellular therapy." (PMID 27400873, 2016). "As vitamin C is a major contributor to TAC from supplements, this finding is supported by the report that vitamin C supplementation had beneficial effects on lowering fasting insulin levels by improving endothelium-dependent vasodilation in patients with non-insulin-dependent diabetes mellitus." (PMID 26742057, 2016). "It is possible that for some people with diabetes who consume quail eggs and are also taking oral hypoglycemic agents or insulin, the components of quail eggs could have a synergistic effect with the bioactive compounds contained in drug formulations." (PMID 27717410, 2016). "Furthermore, a CGMS improves the glycaemic profiles of pregnant women with insulin-treated diabetes." (PMID 26814139, 2016). "Moreover, chronic insulin treatment or suppression of hypothalamic AMPK activity completely prevents diabetes-induced changes in food intake as well as in hypothalamic AMPK activity." (PMID 27547453, 2016). "Diabetes arises as a consequence of combined abnormalities in insulin production and function." (PMID 27572106, 2016). "Time to insulin and age at diagnosis performed best in predicting long-term endogenous insulin production (ROC AUC = 0.904 and 0.871); BMI was a less strong predictor of diabetes type (AUC = 0.824)." (PMID 27080317, 2016).
diabetes (continued). "Some patients progress to insulin-dependent, ketosis-resistant, diabetes mellitus." (PMID 27957355, 2016). "There was also a time-dependent decrease in insulin granule density, as shown by electron microscopy (EM), and a gradual development of large areas of unstructured cytoplasm in β-cells that increased with the duration of diabetes." (PMID 27882918, 2016). "Furthermore, anti-insulin immunoglobulin G (IgG) antibodies and anti-insulin receptor antibodies are occasionally detected in patients with diabetes who have brittle glycemic control or severe insulin resistance." (PMID 27456688, 2016). "The intraperitoneal STZ injection induced hyperglycaemia (diabetes) in rats by damaging the pancreatic β-cell function, resulting in significantly decreased serum insulin concentration (by 73 %), increased plasma glucose level (by 46 %) as well as decreased serum Zn concentration (by 20 %)." (PMID 27071614, 2016). "These are mainly related to apps where errors in the apps or erroneous use may lead to substantial health risks, such as apps for calculating insulin dosages for people with diabetes." (PMID 27052946, 2016). "Younger age, lower baseline HbA1c and baseline serum glucose levels, higher baseline serum insulin levels, and use of biguanides, but not insulin or insulin-sensitising agents, were all associated with diabetes remission." (PMID 29263820, 2016). "In case of diabetes, hepatic toxic events may occur in response to an excess in free fatty acids results of insulin impairment." (PMID 26839634, 2016). "Insulin secretion from pancreatic β-cells is impaired in all forms of diabetes." (PMID 27882918, 2016). "Irisin, a newly identified myokine, was reported to increase total energy expenditure, improve glucose tolerance and reduce fasting insulin, drive brown fat-like development of white fat and then protect diet-induced obesity and diabetes in mouse models in 2012." (PMID 27473122, 2016). "Similarly in glomeruli, many reports suggest that insulin signaling is altered in insulin resistance and diabetes." (PMID 27247938, 2016). "Previous studies have reported that various inflammation markers, e.g., interleukin-6, tumor necrosis factor α (TNFα) and CRP are associated with diabetes It is believed that TNFα contributes to diabetes through its interaction with insulin signaling pathways and beta-cell function." (PMID 26891449, 2016). "In the regression model, the variables independently associated to Spoken Knowledge in Low Literacy Patients with Diabetes were schooling (B=0.193; p=0.003), use of insulin (B=1.326; p=0.004), duration of diabetes (B=0.053; p=0.022) and health literacy (B=0.108; p=0.021)." (PMID 28076599, 2016). "We hypothesized that the FINDRISC is likely to be a marker of impaired insulin secretion since insulin secretion defect is needed for the conversion to diabetes." (PMID 27851812, 2016). "Therefore, we highlight a new, safer therapeutics concept that a low dosage of insulin combined with the trace element selenium can be used for long-term diabetes treatment." (PMID 27212152, 2016). "Impaired glucose homeostasis leads to diabetes and cardiovascular disease and has two main components: failure to secrete enough insulin from pancreatic β-cells and reduced insulin-stimulated cellular uptake of glucose and other nutrients in target tissues (insulin resistance, IR)." (PMID 27768686, 2016). "Therefore, the elucidation of mechanisms and molecules, which play a role in the control of insulin synthesis and secretion, is paramount in order to further our understanding of the pathophysiology of both diabetes and PanNETs." (PMID 26824039, 2016). "Diabetes Mellitus (DM) is a group of metabolic diseases of heterogeneous etiology characterized by poor metabolic control of patients and the presence of marked hyperglycemia, which stems from defects in insulin secretion and/or action." (PMID 27881117, 2016).
diabetes (continued). "However, since glucose itself is a major stimulus of β cells, insulin secretion is augmented by the higher glucose level seen in patients with diabetes." (PMID 27196896, 2016). "A power outage can impact on refrigeration of insulin for people with diabetes." (PMID 28239511, 2016). "Accordingly, the fast progression in the field of biotechnology has inspired the researchers to exert much effort on application of gene therapy, cell therapy and tissue engineering in diabetes therapy, in particular, to develop insulin producing cells using stem cell technology." (PMID 26907255, 2016). "As the subject's mother had the same mutation and a diagnosis of diabetes as well, a trial of sulfonylureas while weaning insulin was attempted without success, suggesting that this variant is not pathogenic." (PMID 26059258, 2016). "However, amylin expression remained relatively stable and amylin+/insulin- islets were observed throughout the pancreas well after diabetes was established." (PMID 27111653, 2016). "Impaired proximal insulin signaling is often present in diabetes." (PMID 27537838, 2016). "It is clear from the literature that reduced insulin signalling is implicated not just in the aetiology of diabetes but also in the pathogenesis of diabetic complications." (PMID 27514532, 2016). "Our results suggest that keeping the percentage of basal insulin below 40% and encouraging the patient to bolus more frequently may lead to less weight gain with improved Diabetes control." (PMID 27777901, 2016). "AD like diabetes mellitus is associated with insulin resistance, except brain rather than skeletal muscle is the principal organ." (PMID 27525190, 2016). "Furthermore, 31.4% had altered fasting glycemia and 8.9% had the diagnosis of diabetes mellitus (DM), but only 7.5% was taking oral antihyperglycemic agents and only 2.8% was taking insulin." (PMID 26919174, 2016). "These efforts spanned virtually all demographics of interest in diabetes studies: healthy women, healthy men, men with type 2 diabetes, women with type 2 diabetes, people with type 2 diabetes on insulin, men with metabolic syndrome, patients with type 1 diabetes, and healthy postmenopausal women." (PMID 27073714, 2016). "Finally, some genetic data now suggest a link between diabetes and AD, as in the case of the insulin degrading enzyme gene or, more recently the SorCS1 gene which is thought to regulate Aβ metabolism (Laneet al., 2010;Laneet al., 2013)." (PMID 27303627, 2016). "The questions were mapped to the following ILOs: diagnosing and managing DKA, prescribing IV fluids for patients with diabetes managing patients on IV insulin, diagnosing and managing HHS, managing patients on oral hypoglycaemic agents and altering diabetes therapy prior to surgery." (PMID 26956764, 2016). "Although cross-sectional studies have established the relationship between diabetes and depression, whether alterations in insulin sensitivity and insulin secretion are present in individuals with MDD is uncertain." (PMID 27274905, 2016). "Hence, they have promoted the development of novel glucose measurement and insulin delivery modalities which hold the potential to dramatically improve the quality of life for diabetics." (PMID 27792179, 2016). "Insulin was applied 2 weeks after induction of diabetes with STZ." (PMID 27253523, 2016). "Unlike verbal IQ, current cognitive status, measured by MMSE, was associated with diabetes only, not with BMI or insulin." (PMID 27642517, 2016). "Among participants with self-reported diabetes, the median age at diagnosis was 53 (range 4 to 77) y, and the median duration of diabetes at baseline was 4 (range 0 to 56) y, with 76% (n = 8,501) reporting use of insulin or oral hypoglycaemic agents." (PMID 27379518, 2016). "Moreover, insulin has been shown to be actively transported into milk and maternal diabetes affect milk insulin levels." (PMID 27213440, 2016).
diabetes (continued). "The study showed that insulin resistance, the lipid ratios (TG/HDL-C, TC/HDL-C, LDL-C/HDL-C) and TG increased, while basal, early-phase, and total phase insulin secretion decreased in the population with different glucose tolerance status from normal plasma glucose to diabetes." (PMID 27267043, 2016). "Thus, CTB-Ins-GAD and CTB-GAD-Ins are much more effective for the suppression of diabetes than insulin or GAD65 single-antigen treatment." (PMID 26783749, 2016). "However, they are related to diabetes or insulin secretion (rs757110 in ABCC8, rs5215 and rs5219 in KCNJ11), carotid intima media thickness (rs2468844 in SAA2), and oligospermia (rs11703684 in PIWIL3)." (PMID 27900359, 2016). "Secreted adipokines interfere with insulin signaling by causing insulin resistance, which in turn leads to an increase in demand for insulin production, leading to type 2 diabetes mellitus (T2DM) if production is not able to meet the demand." (PMID 26797605, 2016). "Several molecular mechanisms have been proposed regarding insulin and its protective effects (glycaemic control) and risks (anabolic effect including weight gain, inhibition of lipolysis, and enhanced lipogenesis) on cognition in patients with diabetes." (PMID 27195294, 2016). "This study demonstrates that the UK Practical Classification Guidelines for Diabetes are an accurate means for differentiating between type 1 and type 2 diabetes in most instances, with time to insulin and age at diagnosis being the most discriminatory clinical characteristics." (PMID 27080317, 2016). "Insulin-producing β cells become dedifferentiated during diabetes progression." (PMID 27572106, 2016). "This asynchronous release may correspond to basal insulin secretion, which is increased in diabetic mouse models, and even in early phases of human diabetes, in agreement with our findings." (PMID 27907065, 2016). "However, subgroup analyses revealed that oral insulin delayed diabetes onset for up to 5 years in patients who had high insulin autoantibody levels." (PMID 26783749, 2016). "In addition to causing severe pain and discomfort for the patient, left untreated, chronic pancreatitis will result in the inability to produce insulin and subsequent diabetes." (PMID 26788521, 2016). "Whereas traditional Kit hypomorphic mast cell-deficient strains featured reduced diet-induced obesity and diabetes, a Kit-independent model of mast cell deficiency, Cpa3Cre/+ mice, displayed no alterations in obesity and insulin sensitivity." (PMID 27933062, 2016). "Together, these studies suggest that increases in H2S may be responsible for a reduction in insulin secretion and ultimately the impaired glucose clearance that occurs in diabetes." (PMID 27478532, 2016). "Physiologically, diabetes development involves impaired insulin sensitivity and insulin secretion that first affects post-prandial glycemia, while chronic fasting glycemia may temporarily remain normal." (PMID 27066296, 2016). "In the present study, overweight adults with parameters of the metabolic syndrome responded to EO with a lower diastolic blood pressure and a reduction in blood lipids and serum insulin, which may reduce risk for CVD and type 2 diabetes mellitus." (PMID 26892399, 2016). "Furthermore, anti-insulin immunoglobulin G antibodies are occasionally detected in patients with diabetes." (PMID 27456688, 2016). "Hence, we report a case in which switching to liraglutide therapy ameliorated both the symptoms of insulin allergy with hypereosinophilia and the characteristics of insulin antibodies in a patient with type 2 diabetes mellitus." (PMID 27456688, 2016). "In a large meta-analysis, an association between HCC and SU or insulin use was identified, however subsequent post-hoc analysis did not reveal any significant association between diabetes therapy and HCC." (PMID 26856933, 2016).
diabetes (continued). "Our study provides the first potential insight in possible mechanisms by which tea may affect postprandial insulin sensitivity and, therefore, development and progression of diabetes mellitus type 2." (PMID 27182277, 2016). "In conclusion, long-term administration of GPR55 agonist Abn-CBD and GPR119 agonist AS-1269574 improved glycaemic control in a multiple-low-dose STZ-induced mouse model of diabetes, resulting in decreased plasma glucose and glucagon and improved plasma insulin, GLP-1 and lipid profiles." (PMID 27677765, 2016). "Several groups also reported that human adipose-derived MSCs could differentiate into insulin-producing cells, suggesting MSCs as a source of transplantation material in the treatment of diabetes." (PMID 27313625, 2016). "Interestingly, ADT causes similar comorbidities and side effects from metabolic and physiologic alterations, including increased adipose tissue, cardiovascular disease, QT interval prolongation, insulin insensitivity, and diabetes." (PMID 26977321, 2016). "However, the diabetes stage in our study population was advanced: type 1 and type 2 diabetes patients on at least two insulin injections a day, and a high prevalence of micro- and macrovascular complications." (PMID 27553193, 2016). "This may be due to the authors having excluded patients with the same dates for first prescription of insulin and diabetes diagnosis." (PMID 27861488, 2016). "We can speculate that it is due to their already initial high adaptation to diabetes-related tasks and educational potential and abilities to view and use real-time data to make insulin, nutrition, and lifestyle modifications." (PMID 26649320, 2016). "However, the group with severe hypoglycemia had diabetes longer, and the average daily dose of insulin use was higher than in other groups." (PMID 27994961, 2016). "Leptin treatment appears to be beneficial in such a circumstance, thus this treatment might also be considered in some human diabetes patients with diminished insulin reserve." (PMID 28702245, 2016). "There are few prospective studies on the use of insulin before overt diabetes in patients with CF and they include population with different types of glucose disorders, without age group delimitation, follow-up time, and insulin type, dosage, and implementation schedule." (PMID 26994743, 2016). "For example, a UK-based cohort study which identified 214 incident cancers among 23,834 persons with diabetes diagnosed between 1972 and 1986 and reported a standardised incidence ratio of 0.95 (95% CI 0.84, 1.08), used insulin treatment as a proxy for type 1 diabetes." (PMID 26924393, 2016). "In this study, we have made a preliminary exploration of treatments intended to suppress hyperglucagonemia and control diabetes in conditions of diminished insulin reserve without the risk of fatal hypoglycemia." (PMID 28702245, 2016). "Interestingly the insulin levels in Fukuoka women with diabetes at 6.2 μIU/mL were less than 40% of the values observed in Framingham women with diabetes at 16.3 μIU/mL." (PMID 27830830, 2016). "Moreover, SIRT1 activation reduced diabetes symptoms and insulin secretion and delayed the onset of insulin resistance in diabetic rats." (PMID 27123454, 2016). "Indeed, we identified miR-194 as being down-regulated in skeletal muscle of insulin resistant rats from HF fed dams, high fat fed mice, and humans with pre-diabetes and T2DM." (PMID 27163678, 2016). "The univariate regression analysis demonstrated the following variables were associated with SKILLD: schooling level (B=0.232; p<0.001); marital status - married (B=0.483; p=0.031); use of insulin (B=1.432; p=0.003); duration of diabetes (B=0.071; p=0.005) and SAHLPA-18 (B=0.182; p<0.001)." (PMID 28076599, 2016).